Y_RNA (Y RNA )
Gene: Miscellaneous RNA gene on chromosome 9 (19,089,593 to 19,089,688, forward strand). Ensembl gene ENSG00000201118.
Homologues: Orthologues: chimpanzee Y_RNA (99% identical), macaque Y_RNA (94% identical). Paralogues in human: RNY4P9 (81% identical), Y_RNA (80% identical), Y_RNA (79% identical), RNY4P28 (78% identical), RNY4P29 (78% identical), Y_RNA (78% identical), Y_RNA (77% identical), RNY4 (76% identical), Y_RNA (76% identical), RNY4P30 (75% identical), RNY4P6 (75% identical), RNY4P14 (74% identical), and 88 more.